MIR625 (microRNA 625)
Synonyms: hsa-mir-625; MIRN625
Gene: MicroRNA gene on chromosome 14 (65,471,102 to 65,471,186, forward strand). Ensembl gene ENSG00000207781.
Gene Ontology:
Biological process: miRNA-mediated post-transcriptional gene silencing
Cellular component: RISC complex
Diseases named in the same sentence as MIR625 in open-access papers:
MIR625 is named in the same sentence as 2 diseases in open-access papers, as found by Europe PMC text mining. Sharing a sentence is not in itself a finding about the gene and the disease. The quoted sentences say what the papers report.
colorectal carcinoma (1 paper, 2020). A malignant epithelial neoplasm that arises from the colon or rectum and invades through the muscularis mucosa into the submucosa. "Decreased expression of MIR625 was described in colorectal carcinoma." (PMID 32252688, 2020).
MIR625 also shares sentences with these, for which no sentence is quoted: cancer (1 paper).